RN7SL229P (RNA, 7SL, cytoplasmic 229, pseudogene)
Gene: Miscellaneous RNA gene on chromosome 3 (180,736,405 to 180,736,703, reverse strand). Ensembl gene ENSG00000242811.
Homologues: Orthologues: chimpanzee Metazoa_SRP (98% identical), macaque Metazoa_SRP (91% identical). Paralogues in human: RN7SL2 (81% identical), RN7SL1 (81% identical), RN7SL296P (80% identical), RN7SL3 (80% identical), RN7SL300P (79% identical), RN7SL145P (79% identical), RN7SL127P (79% identical), RN7SL45P (78% identical), RN7SL126P (78% identical), RN7SL44P (78% identical), RN7SL589P (78% identical), RN7SL797P (77% identical), and 700 more.